KRAS (KRas proto-oncogene, GTPase)
Diseases named in the same sentence as KRAS in open-access papers (continued):
Sharing a sentence is not in itself a finding about the gene and the disease.
tumor (continued). "STAT3, a member of signal transducer and growth factors (STAT), is one of the main transcription factors that transmit the signals of several cytokines, particularly IL-6 in KRAS-mutant tumor cells." (PMID 36899885, 2023). "Mutations and aberrant expressions of small GTPases of the Ras superfamily (e.g. KRAS) are acknowledged among the key driving factors for tumour genesis and progression." (PMID 37203239, 2023). "Mutated KRAS and other oncogenes such as EGFR and SRC can transfer to tumor cells through exosomes, promoting colon cancer invasion." (PMID 37305043, 2023). "Since the development of resistances limits the duration of response, a need of combination therapies with inhibitors of pathways involved in tumor immune evasion by KRAS is suggested." (PMID 37347257, 2023). "The complex of PP1 with the leucine-rich repeat protein SHOC2 promotes tumor growth in a subset of KRAS-mutant NSCLC cell lines by dephosphorylating a critical inhibitory site on RAF kinases, resulting in RAF-ERK pathway activation." (PMID 36966223, 2023). "It was shown in an immunocompetent mouse model that the KRAS inhibitor AMG510 led to a more inflamed tumor immune environment, which resulted in a greater efficacy of ICIs." (PMID 36926333, 2023). "Previous studies have found that the KRAS gene acts as a switch in the body, regulating signaling pathways such as tumor cell growth and angiogenesis." (PMID 36776306, 2023). "The KRAS 4B isoform is generally more abundant in CRC than the KRAS 4A isoform, although it varies from tumor to tumor." (PMID 36831298, 2023). "In contrast, when KRAS status and the side of the tumor were compared, wild-type CRCs had left-sided localization (52.4%), whereas mutant-type CRCs had right-sided localization (21.4%) (p = 0.014)." (PMID 37639911, 2023). "Anti-KRAS antibody was internalized into the cytoplasm and formed punctate structures in both the mucosa and tumor." (PMID 37051535, 2023). "RAS mutations are long known to provide radiation resistance to tumor cells, as demonstrated first in mouse cell lines transformed with HRAS, NRAS or KRAS mutations." (PMID 37907934, 2023). "The median KRAS DNA variant allele frequency (VAF), which was used as a surrogate for tumor purity, was 32% (range 20–64%)." (PMID 37179276, 2023). "Of note, adoptive transfer of autologous TIL that is responsive to KRAS p.Gly12Asp neoantigen can result in the tumour regression in patients with metastatic CRC." (PMID 37921274, 2023). "Here, we showed that SLC25A22 knockout synergized with anti-PD1 therapy to mediate tumor regression in KRAS-mutant CRC allograft models, accompanied by synergistic induction of cytotoxic CD8+ T-cell activation." (PMID 37542037, 2023). "For example, treatment of mutant KRAS-driven PDAC tumours with the combination of gemcitabine and SLC-0111 results in acidosis and cell death, and prolongs survival by tumour-bearing mice." (PMID 38099193, 2023). "A key hallmark of KRAS-mutant CRC is metabolic reprogramming to meet bioenergetic, biosynthetic, and redox demands of tumor cells." (PMID 37542037, 2023). "SERPINA1 promotes a better prognosis of PTC-W possibly through tumour inhibition signalling pathways, such as the KRAS and NF-kB signalling pathways." (PMID 37455914, 2023).
tumor (continued). "It has been shown that the combined use of a MEK inhibitor and ABT-263, a chemical inhibitor of Bcl-xL, promotes tumor regression in KRAS mutant cancer models." (PMID 37726310, 2023). "Oncogenic KRAS modulates both the expression of ICMs and the infiltration of TILs, which are important factors of the anti-tumour immune response." (PMID 36864508, 2023). "They observed a reduced tumor burden in KRAS-missense-alteration-carrying cell lines in colon cancer and NSCLC." (PMID 36899885, 2023). "KRAS and/or GNAS mutations are found in >90% of IPMNs, both in those with advanced neoplasia (high-grade dysplasia or adenocarcinoma) and low-grade dysplasia." (PMID 36980608, 2023). "Notwithstanding this, KRAS G12C inhibitors showed clinical efficacy in eradicating micrometastases and enhanced anti-tumor activity when combined with targeted agents." (PMID 37835787, 2023). "The authors suggested that tumor inhibition was driven by MEK in BRAF-mutant models and by Aurora kinases in models mutated for KRAS." (PMID 37830744, 2023). "Our findings identify signaling pathways and cytokines impacted by HES1 that are responsible for promoting tumor progression in KRAS mutant CRCs." (PMID 37749297, 2023). "miR-206 acts as a tumor suppressor in PC and was found to inhibit both the KRAS and ANXA2 oncogenes." (PMID 38130990, 2023). "KRAS G12D induced macrophages to switch to a pro-tumor M2 phenotype through STAT3-dependent fatty acid oxidation." (PMID 37670322, 2023). "For example, in PC, it is conceivable that TGF-β induces EMT from an early stage due to KRAS abnormalities and shifts from a tumor suppressor to a tumor promoter." (PMID 37892233, 2023). "Tumor suppressive effects were also highly correlated between KRAS G12C-driven tumors at 15 weeks post-tumor initiation and KRAS G12D-driven tumors at 9 weeks post-tumor initiation, when sgInert tumors were most similar in size (Spearman ρ = 0.90)." (PMID 37828026, 2023). "The two groups were compared for variables of age, gender, tumor location, histology, depth of tumor invasion, lymph node metastasis, lymph invasion, venous invasion, distant metastasis, CEA level, and KRAS, NRAS, and HRAS mutations." (PMID 37758931, 2023). "Taken together, these data indicate that 1-2C and 3-2E TCR-T cells specifically recognized and responded to eliminate tumor cells with KRAS-G12V in the context of HLA-A*11:01." (PMID 37828002, 2023). "By inspecting their oncoprint, 27/59 tumours harboured mutations in either SOX9 or MYC and were wild-type in either BRAF, KRAS or NRAS, hinting towards an alternative cetuximab resistance mechanism." (PMID 37666855, 2023). "In fact, KRAS-mutant CRC has been reported to harbor a more immunosuppressive tumor microenvironment, which limits the use of immune checkpoint inhibitors as monotherapy." (PMID 37511664, 2023). "This claim is in part supported by two other recent reports where it is shown that KRAS mutated NSCLCs exhibit increased FASN levels and its inhibition results in decreased tumor formation." (PMID 36675307, 2023). "T-cell engagers (BiTE) have been generated from these antibodies, which can direct T-cell–mediated killing of KRAS G12C tumor cells." (PMID 37581538, 2023). "We also carried out stratified analyses by (a) sex, (b) tumor stage, (c) tumor grade, (d) MSI status, and by (e) KRAS mutation status." (PMID 37296884, 2023).
tumor (continued). "In human CRC specimens, a significant reduction in cytotoxic CD8+ T‐cell tumor infiltration is found in patients with mutant versus wild type KRAS." (PMID 36599679, 2023). "We showed that anti-KRAS antibody can enter live mucosa-tumor cells and specifically aggregate KRAS in the cytoplasm, thus hindering its translocation to the inner plasma membrane." (PMID 37051535, 2023). "Constitutive activation of KRAS plays a key role in metabolic reprogramming, in particular, the glycolytic switch to support the synthesis of tumor biomass." (PMID 37559908, 2023). "Chi-squared test was used to assess the correlation between KRAS status and patient-tumor characteristics (age, sex, location of the primary tumor, and metastatic spread)." (PMID 36788889, 2023). "Contrary to our expectation that inactivation of these negative regulators would have a greater effect on tumors driven by the weaker KRAS G12C variant, inactivation of Nf1 or KrasWT increased KRAS G12C- and KRAS G12D-driven tumor growth to the same extent." (PMID 37828026, 2023). "KRAS mutant tumor cells have been shown to exhibit greater sensitivity to MEK inhibitors compared to KRAS wild-type cell lines." (PMID 37941550, 2023). "Using the pre-amplification method, tumor-derived mutant KRAS in the plasma of patients with resectable PDAC was accurately detected (AUC, 0.861–0.876), and the dPCR method improved post-resection recurrence prediction over that of the marker CA19-9." (PMID 37470859, 2023). "For the KRAS G12C inhibitors tumor responses are short-lived with only 5–6 months due to emerging chemoresistance to monotherapy." (PMID 38023987, 2023). "EphA2 is highly expressed in many KRAS-mutant LC cells and has been shown to regulate tumor malignancy." (PMID 37370855, 2023). "Mutant KRAS-IL-1β addiction is mediated via secretion of the glycoprotein versican (VCAN) by tumor cells, which inhibits the NF-κΒ kinase (IKK) β in macrophages, resulting in IL-1β release into the tumor microenvironment." (PMID 36980752, 2023). "KRAS mutations in UrC have been extensively investigated, as it is a commonly affected oncogene in CRC, a tumour type sharing large histological and molecular similarities with UrC." (PMID 36670542, 2023). "Based on these data, we propose that pro-ferroptotic therapy for KRAS-driven cancers should include inhibition of FSP1 in order to achieve efficient tumor cell killing." (PMID 36443441, 2023). "That is, FSP1 expression was sufficient in KRAS-mutated LUAD to significantly promote 3D spheroid growth in vitro and accelerate tumor onset in vivo by protecting from ferroptosis." (PMID 37834062, 2023). "In P6, however, tumor KRAS profiling was performed 7 months after ctDNA testing at the time of tumor progression." (PMID 37511664, 2023). "Both the tumor and matched mucosa crypt epithelial live cells were treated with anti-KRAS antibodies." (PMID 37051535, 2023). "The dynamic modulation of optimal total and mutant Ras dosage has been elegantly demonstrated in the characterization of allelic imbalances in mutant versus wild type KRAS during tumor outgrowth and in response to therapy in a mouse model." (PMID 36864243, 2023). "The combination of cetuximab and sotorasib inhibited the activation of the EGFR-driven MAPK pathway in these cells, thus sustaining downstream target inhibition, considerably increasing KRAS G12C inhibition and leading to tumor regression." (PMID 37569406, 2023). "Further experiments also failed to observe increased tumor T-cell infiltration, decreased Treg cells, and downregulation of PD-L1 in tumor cells in KRAS-mutant GEMM." (PMID 36966334, 2023).
tumor (continued). "The first study of note is an attempt by Liu and colleagues who noted KRAS-G12D mutation responsible for suppressing the PD-L1 targeted therapy and CXCL10/CXCL11 (chemokines) secretion, together suppressing the CD8+ tumor infiltrating lymphocytes (TILs)." (PMID 37970206, 2023). "These iRGD exosomes were used to specifically target αvβ3-harboring A549 tumors via delivering the KRAS siRNA in vivo, which resulted in tumor suppression via the knocking down of the KRAS gene." (PMID 37345176, 2023). "KRAS mRNA levels in different tumor samples paired with normal tissues and KRAS expression between tumor and non-tumor-matched GTEx normal tissues were not significantly different." (PMID 38206735, 2023). "Yet strikingly, FSP1 expression was sufficient in KRAS WT cells to significantly accelerate tumor onset and increase tumor incidence closer to the rates of KRAS-mutant tumors." (PMID 36443441, 2023). "Collectively, these results indicate that different oncogenes in the EGFR/KRAS/BRAF axis have dramatically different effects on tumor initiation and growth." (PMID 37828026, 2023). "In another study, in vitro and in vivo studies of the second-generation KRAS-G12C-inhibitor ARS1620 in combination with PI3K inhibitors resulted in tumor regression in KRAS-mutant NSCLC." (PMID 36899885, 2023). "Conventional histological tumour staging, BRAF mutations, KRAS mutations, MSI status and TSR were determined." (PMID 37344790, 2023). "We first determined the subcellular localization of KRAS in the ex vivo tumor and matched mucosa cells." (PMID 37051535, 2023). "Even before tumor occurrence, KRAS inhibition reduced the number of Treg induced by tobacco carcinogen NNK in lung tissue." (PMID 37670322, 2023). "Before exploring the impact of inactivation of each tumor suppressor gene on tumor growth, we restricted our analysis to these sgInert “KRAS-only” tumors." (PMID 37828026, 2023). "The punctate staining indicates that the anti-KRAS antibody was internalized into both the mucosal and tumor cells." (PMID 37051535, 2023). "This process is driven through increasing TGFβ signalling and enables KRAS-independent tumour progression." (PMID 36864508, 2023). "This resulted in an upregulation of T cell chemo-attractants such as Cxcl9/10/11 and antigen presentation genes including H2-d/k1, Ciita, and B2m, thus demonstrating how even neoantigen-high KRAS-mutant tumours can escape the adaptive immune response." (PMID 36864508, 2023). "Cetuximab presents relatively great therapeutic effect only among KRAS wide-type CRC patients while the KRAS mutant-type CRC patients show cetuximab resistance, for mutant KRAS and downstream pathways are activated and the tumor cell proliferates constantly." (PMID 36639711, 2023). "The associations were significant even after stratification by sex, tumor stage, grade, MSI status, and KRAS mutation status." (PMID 37296884, 2023). "Mutated KRAS makes up about 85% of all RAS mutations and has been previously associated with clonal expansion of anti-tumor T cells in human patients." (PMID 37776855, 2023). "Specifically, mutant KRAS not only alters the behavior of cancer cells but also affects various cells in the tumor microenvironment (TME)." (PMID 37662925, 2023). "Collectively, these data support the potential for leveraging the innate immune system, particularly NK cells, in the treatment of KRAS-mutant tumours." (PMID 36864508, 2023).
tumor (continued). "P4 and P5 had primary tumors resected before ctDNA testing, and the tumor tissues tested positive for KRAS p.G12D and KRAS p.G12S, respectively." (PMID 37511664, 2023). "Much work on improving targeting specificity and efficient delivery to tumor tissues will be required for the CRISPR system to emerge as a viable clinical intervention for KRAS mutant cancers." (PMID 38069255, 2023). "The antiproliferative effect of treatment varied in KRAS mutant models, a finding that is in agreement with previous reports suggesting that only some KRAS mutant tumours depend on KRAS for their growth." (PMID 37258666, 2023). "In summary, our results show that the ablation of N-WASP expression accelerates KRas-mutant-induced tumor formation through the activation of the EGFR-KRas signaling pathway." (PMID 37760426, 2023). "For example, patients with KRAS/RAS-wt mCRC treated with first-line EGFR-I plus chemotherapy with a LSC primary tumor showed improved results in a drug trial when compared to RSC patients." (PMID 37749112, 2023). "Comparing size distributions of tumors of each tumor suppressor genotype revealed consistent effects between KRAS G12C- and KRAS G12D-driven lung tumors." (PMID 37828026, 2023). "This study revealed promising anti-tumor activity by CDK9-targeting compounds as a potential therapeutic strategy for KRAS-mutant CRC." (PMID 37569406, 2023). "To further investigate the different abilities of oncogenic KRAS G12C and KRAS G12D to initiate lung tumors and drive their growth, we explored the distribution of sgInert tumor sizes." (PMID 37828026, 2023). "PC is a molecular heterogeneous disease, and the oncogenic gene KRAS is a powerful driver of tumor initiation and maintenance." (PMID 38081815, 2023). "We treated the KRAS p.Gly12Val tumor cells with mouse anti-KRAS antibody, then fixed and immunostained for KRAS using rabbit anti-KRAS antibodies." (PMID 37051535, 2023). "Preclinical investigations with human pancreatic ductal adenocarcinoma (PDAC) cells have shown that oncogenic KRAS mutations reprogram glutamine metabolism through an alternative pathway that fuels the tricarboxylic acid (TCA) cycle and promotes tumor growth." (PMID 37239063, 2023). "In preclinical data, KRAS G12C direct inhibitors have been shown to upregulate a pro-inflammatory tumor microenvironment and increase anti-tumor T-cell activity." (PMID 37835787, 2023). "Most of the reported mutated genes were reported in both the primary and metastasis tissues, except KRAS G12A and NEK E379K mutations that were found in primary tumors and CCND1 G103R in the metastasis tumor." (PMID 38003476, 2023). "Codons 12/13 in exon 2 of the KRAS gene lead to continuous activation of the EGFR signaling pathway that accelerates tumor cell proliferation." (PMID 37924117, 2023). "Of the CRC cases with molecular tumor data, 20% were BRAF mutated, 23% were KRAS mutated, and 13% were MSI." (PMID 37849011, 2023). "Gain of the region of chromosome 12p containing the KRAS oncogene was seen in 42% of tumours, occurring subclonally in 38% of cases." (PMID 37081523, 2023). "Using high-resolution melt curve analysis and pyrosequencing methods, mutations in KRAS are detected in PJ from PDAC patients and in 50% of asymptomatic individuals at high risk for neoplasms." (PMID 37470859, 2023).